GLP1R (glucagon like peptide 1 receptor)
Diseases named in the same sentence as GLP1R in open-access papers (continued):
Sharing a sentence is not in itself a finding about the gene and the disease.
diabetes (continued). "Glucagon-like peptide-1 receptor (GLP-1R) agonists are in clinical use for glycemic control in diabetes and are also known to modulate microglia." (PMID 34673570, 2021). "Sodium-glucose transporter 2 inhibitors and glucagon-like peptide 1 receptor agonists have recently shown potential efficacy for the treatment of NAFLD/NASH with diabetes, but are expected to be more effective for NAFLD/NASH in obese diabetic patients." (PMID 33691757, 2021). "Glucagon-like peptide-1 receptor agonists (GLP-1RAs) are used to treat diabetes and obesity and reduce rates of major cardiovascular events, such as stroke and myocardial infarction." (PMID 34673572, 2021). "Among the several pharmacological treatments for the therapy of diabetes, GLP-1 receptor (GLP-1R) agonists are being used, with a favorable benefit/risk ratio." (PMID 34575477, 2021). "In HUVECs cultures GIP/GIPR and GLP1/GLP1R interactions reduce the advanced glycation end products (AGEs) receptor (RAGE) expression, blocking the signalling pathways associated with diabetes-associated vascular damage." (PMID 33440821, 2021). "In the past decade, multiple pharmacokinetically optimized GLP-1 receptor (GLP-1R) agonists (GLP-1RAs) have been approved for the clinical treatment of diabetes mellitus." (PMID 34079050, 2021). "With their high efficacy for glycemic control, GLP-1R agonists, including exenatide, are in common clinical use for patients with diabetes." (PMID 34673570, 2021). "Taken together, these findings suggest that GLP-1R agonists have a dual effect (neuroprotective and vasculotropic) which ameliorates the diabetes-induced impairment of the neurovascular unit." (PMID 34440130, 2021). "Given the implication of GLP-1R involvement in the aetiology of bone fragility in diabetes, research has explored the possibility of GLP-1R agonist or DPP-4 inhibitor use in the management of the condition with favourable outcomes." (PMID 34093449, 2021). "This review focuses on recent advances in non-invasive in vivo β-cell imaging for BCM evaluation in the field of diabetes; in particular, the exendin-based GLP-1R-targeted nuclear medicine techniques." (PMID 34248856, 2021). "Despite the importance of these drug classes for the treatment of diabetes and obesity, still very little is known about the localization of GLP1R and GIPR themselves." (PMID 34911028, 2021). "Glucagon-like peptide-1 receptor agonist (GLP-1 RA) is probably one of more effective antidiabetic agents in treatment of type 2 diabetes mellitus (T2D)." (PMID 35095773, 2021). "In our study, GLP-1R protein level was increased accompanied with increased mRNA expression of Glp-1r in combination therapy in an early phase of diabetes." (PMID 34373487, 2021). "GLP-1R is a G-protein-coupled receptor that plays a key role in glucose metabolism and is a major therapeutic target for diabetes." (PMID 34248856, 2021). "This section reviewed the clinical studies on the effects of the GLP-1R agonist on cardiovascular diseases in healthy individuals and patients with diabetes." (PMID 34258291, 2021). "Patients with hypertension, diabetes, and obesity frequently use glucagon-like peptide-1 receptor (GLP-1R) agonists, angiotensin receptor blockers (ARBs), and ACE inhibitors (ACEIs)." (PMID 34285709, 2021). "GLP-1R induction has been reported to protect renal tissue and improve kidney function from diabetes-induced dysfunction via several molecular mechanisms that have been detailed in the following paragraphs." (PMID 34471642, 2021). "The remarkable finding that in β-cells GLP-1R coupling switches during diabetes pathogenesis adds impetus to understand in more detail the mechanism and pathways of Gαs- and Gαq-dependent signaling in β-cell." (PMID 33935974, 2021).
diabetes (continued). "Intriguing, glucose-lowering drugs, especially cardiovascular beneficial agents, such as glucagon-like peptide-1 receptor agonists and sodium glucose co-transporter inhibitors, have been shown to exert direct anticoagulation effects in patients with diabetes." (PMID 34072487, 2021). "The incretin-based therapies, which include DPP-IV inhibitors and GLP-1 receptor (GLP-1R) agonists, are a new class of antidiabetic medications, which aim to ameliorate the “incretin defect” present in people with diabetes." (PMID 33123598, 2020). "The clinical value of targeting GLP-1R has been demonstrated in diabetes with medicinal products used to stimulate insulin release, and in cancer for diagnostic imaging of e.g. insulinoma tumors." (PMID 31903131, 2020). "Glucagon-like peptide-1 receptor (GLP-1 R) agonist is currently approved for the treatment of diabetes." (PMID 32832307, 2020). "Liraglutide is a glucagon-like peptide-1 receptor agonist (GLP-1 RA) suitable for once-daily administration in patients with type-2 diabetes mellitus (T2DM)." (PMID 33008044, 2020). "The capacity of the tri-agonist to prevent the development of spontaneous diabetes compared with the dual incretin GLP-1R/GIPR co-agonist was also tested in mouse models of T2D." (PMID 32269764, 2020). "Overall, our results emphasize the therapeutic potential of MS-275 as an adjunct to GLP-1R therapy in the treatment of diabetes and obesity." (PMID 33349332, 2020). "GLP-1R agonists target many anti-inflammatory pathways in animals and lessen systemic inflammation in individuals affected by diabetes and obesity." (PMID 33335527, 2020). "Other treatment options available for diabetes control besides insulin have proven to be beneficial in reducing GV and inflammation including glucagon-like peptide-1 receptor antagonists (GLP-1 RA)." (PMID 33371247, 2020). "Using these freely available probes, we provide an updated view of GLP1R organization, with relevance for the treatment of complex metabolic diseases such as obesity and diabetes." (PMID 31980626, 2020). "Glucagon-like peptide-1 receptor agonists have become established as a leading class of diabetes medications." (PMID 33177239, 2020). "Double-labeling fluorescence IHC of pancreata from healthy humans and those with diabetes showed complete co-localization of the GLP-1R and insulin in all islets and islet-like samples." (PMID 31031702, 2019). "Decades of animal and human research in the field of gut hormones have produced effective and safe therapies for the treatment of diabetes and obesity with the GLP1R agonists now accepted as routine treatments for diabetes and obesity." (PMID 30466162, 2019). "Both effects, from incretin hormones and glucagon were used to develop anti-diabetes agents: GLP1R and GIPR agonists or antagonists and GCGR antagonists." (PMID 30650080, 2019). "GLP-1R agonists ameliorate both diabetes and obesity, decrease cardiovascular events, stroke and nephropathy in clinical trials and ameliorate dementia and stroke in preclinical studies." (PMID 29317623, 2018). "Modified GLP-1 receptor (GLP-1R) agonists are commercially available for the treatment of diabetes and obesity." (PMID 29782892, 2018). "Glucagon-like peptide-1 receptor agonists (GLP-1RAs) are desirable for diabetes, especially in patients with overweight/obesity." (PMID 29167470, 2017). "The use of Ex-4 and liraglutide, two GLP-1R agonists, for treatment of diabetes produced small yet significant reductions in body weight." (PMID 28223965, 2017). "In fact, treatment with GLP-1R agonists increases β-cell proliferation in animal models of diabetes." (PMID 28717164, 2017). "In conclusion, impaired healing of chronic gastric ulcer in subjects with diabetes is potentiated by parenteral administration of a Glp-1R analogue Ex4." (PMID 29095895, 2017).
diabetes (continued). "Our data elucidates important mechanism underlying the effects of exendin-4 on adiponectin level both in vitro and in vivo, and shed light on new treatments of diabetes based on exendin-4/GLP-1R functions." (PMID 28122026, 2017). "Starting in the late 1990s, GLP-1R gained attention as a potential therapeutic target for AD, since diabetes and AD share similar pathological features, including chronic oxidative stress and inflammatory responses." (PMID 28846606, 2017). "Glucagon-like peptide-1 receptor agonists (GLP-1RAs), which have valid glucose-lowering efficacies as well as notable weight-loss effects, are beneficial for diabetes therapy, especially for patients with overweight/obesity." (PMID 29167470, 2017). "Exendin-4 (Ex-4), a glucagon-like peptide-1 receptor agonist, is known to have many beneficial effects on diabetes." (PMID 28202074, 2017). "A molecular-level understanding of function and activation mechanism of GLP1R can aid rational design of drugs targeting GLP1R for diabetes treatment." (PMID 28609478, 2017). "The differential effects were attributable to reduced GLP-1R expression in diabetic islets, which agreed with β cell dysfunction during diabetes progression." (PMID 28801559, 2017). "Glucagon-like peptide-1 receptor (GLP-1R) agonists have been in clinical use for the treatment of diabetes and also been reported to be neuroprotective in ischemic stroke." (PMID 26863436, 2016). "GLP-1R plays a central role in post-prandial insulin release; the inhibition of gastric emptying; the inhibition of glucagon secretion and the reduction of food intake, thus GLP-1R is an important pharmaceutical target for diabetes therapy." (PMID 27917297, 2016). "The GLP-1 receptor GLP1R is probably the best characterised GPCR to have been harnessed to date for the treatment of diabetes." (PMID 26661410, 2016). "This study is the first to examine the effect of different types of experimental diabetes on GLP-1R expression in an extrapancreatic target organ of the enteropancreatic axis, namely, the glandular stomach." (PMID 25893200, 2015). "Together, these findings suggest potential opportunities for employing combination treatments that comprise parallel MC4R and GLP-1R agonism for the treatment of obesity and diabetes." (PMID 25652173, 2015). "In contrast, SPD rats with STZ-induced diabetes demonstrated a significantly decreased number of their glandular GLP-1R bearing cells in the same area compared with normoglycemic nondiabetic controls (P < 0.05)." (PMID 25893200, 2015). "In conclusion, nutrient and chemical induced experimental diabetes result in distinct opposite alterations of GLP-1R expression in glandular stomach." (PMID 25893200, 2015). "This study assessed extrapancreatic GLP-1R system in glandular stomach of rodents with different types of experimental diabetes." (PMID 25893200, 2015). "HE diet-induced diabetes resulted in significantly increased frequency of GLP-1R immunoreactive cells in neck area of the glands in PO compared with normoglycemic control PO (P < 0.01)." (PMID 25893200, 2015). "To estimate impact of HE-diet and STZ-induced diabetes on gastric glands GLP-1R expression we performed semiquantitative and quantitative microscopic analysis of GLP-1R immunoreactive glandular cells." (PMID 25893200, 2015). "This is the first study to demonstrate significantly enhanced efficacy that results from combining MC4R and GLP-1R agonism for the treatment of obesity and diabetes." (PMID 25652173, 2015). "So, exogenous GLP-1R agonists have been more recently considered as a good choice for treating patients with diabetes." (PMID 25338737, 2014). "Targeting of glucagon-like peptide-1 receptor (GLP-1R) has been developed to complement conventional treatment options for diabetes mellitus." (PMID 25407893, 2014).
diabetes (continued). "With dual GLP-1R and amylin agonists we have harnessed the integrated and neurohormonal control of diabetes, and potentially obesity and related disorders, in a single molecular entity." (PMID 24167604, 2013). "For patients with diabetes, GLP-1R agonists have been shown to improve glycaemic control in a regulated manner; lowering elevated blood glucose while maintaining sufficient concentrations for optimal metabolic function." (PMID 22776039, 2013). "Recently, treatment with exedin-4 (a long-acting agonist of GLP-1R) was shown to reduce development of diabetic retinopathy ([DR], one of the commonest complications of diabetes) in animal models of diabetes." (PMID 24307763, 2013). "Exenatide (synthetic exendin-4) is a glucagon-like peptide-1 receptor (GLP-1R) agonist developed as a first-in-class diabetes therapy." (PMID 23256660, 2013). "Discovery of the pleiotrophic effects of GLP-1 on blood glucose control led to the development of GLP-1R agonists with extended half-lives for the treatment of diabetes." (PMID 21167014, 2012). "Incretin-based therapies have established a foothold in the diabetes armamentarium through the introduction of oral dipeptidyl peptidase-4 inhibitors and the injectable class, the glucagon-like peptide-1 receptor agonists." (PMID 21707956, 2012). "With regard to the increasing and successful use of GLP-1 analogs for diabetes therapy, it is worth keeping in mind that selected cancers can overexpress GLP-1R." (PMID 23230431, 2012). "The GLP-1R is of clinical interest not only due to its physiologic expression and functions in pancreatic islet cells and its potential in diabetes therapy, but also because of its possible role in cancer." (PMID 23230431, 2012). "Glucagon-like peptide-1 receptor agonists (GLP-1 RA) are effective for obese patients with type 2 diabetes mellitus (T2DM) because they concomitantly target obesity and dysglycaemia." (PMID 23236362, 2012). "If GLP-1R agonists were to be used continuously to treat diabetes, then uncontrolled beta-cell proliferation would become an issue unless there were brakes on the system." (PMID 21716694, 2011). "Therefore, finding signaling pathways and mechanisms that can restore responses to GLP-1R agonists will have major implications for diabetes treatment." (PMID 41480766, 2026). "In addition, the article reviews the clinical progress of GLP-1R agonists, including their efficacy, safety and potential in the treatment of diabetes and related complications." (PMID 40520185, 2025). "In a diabetes-driven kidney disease model, Glp1r–/– mice with streptozotocin-induced diabetes exhibited spontaneous kidney dysfunction and accelerated kidney damage as evidenced by their higher albumin-to-creatinine ratios, increased fibronectin levels, and lower cystatin C levels in the urine." (PMID 41178710, 2025). "Importantly, a recent retrospective study had found that GLP-1 RAs reduced suicidal ideation in large cohorts of overweight or T2D patients compared to non-GLP-1R agonist anti-obesity or anti-diabetes medications." (PMID 41331950, 2025). "We show that HISHS‐2001 (GL0059) displays higher GLP‐1R affinity and bias towards cAMP production over β‐arrestin 2 recruitment, as well as comparable or improved metabolic effects in the db/db mouse model of diabetes versus tirzepatide." (PMID 40831316, 2025). "We investigated whether the peripheral co-administration of leptin and liraglutide (a glucagon-like peptide-1 receptor agonist) improved glucose metabolism in a mouse model of insulin-dependent diabetes mellitus (IDDM)." (PMID 40429740, 2025). "Semaglutide, originally developed for the treatment of diabetes, was approved by the FDA on 4 June 2021 as a weight-loss medication due to its ability to activate glucagon-like peptide-1 receptor (GLP1R) in the central nervous system, reducing food intake and promoting weight loss." (PMID 40141382, 2025).
diabetes (continued). "The second trend can be linked to significant development and interest in peroxisome proliferator-activated receptor and glucagon-like peptide-1 receptor agonists, dipeptidyl peptidase IV and sodium glucose co-transporter inhibitors, all of which address carbohydrate metabolism and diabetes." (PMID 39780999, 2025). "Fifth, approximately half of the participants had diabetes, and some of them were treated with glucose-lowering agents including sodium-glucose cotransporter-2 inhibitors and glucagon-like peptide-1 receptor agonists, which may affect hepatic steatosis." (PMID 40375947, 2025). "Diabetes medications such as sodium–glucose cotransporter 2 inhibitors and glucagon-like-peptide-1 receptor agonists are known to exhibit favorable cardioprotective effects and could potentially impact the observed associations." (PMID 40283627, 2025). "GLP-1R agonists have emerged as a significant therapeutic agent in the management of diabetes." (PMID 40520185, 2025). "Previous studies on TAA-induced cirrhosis in male rats have shown beneficial effects on PH using drugs like obeticholic acid, a potent and selective FXR agonist involved in bile acid and lipid metabolism, and liraglutide, a glucagon-like peptide-1 receptor agonist used in diabetes treatment." (PMID 40462236, 2025). "In addition, GLP-1R agonists help treat diabetes by protecting the brain and heart, preserving kidney function and aiding weight loss." (PMID 40520185, 2025). "Given that contemporary diabetes management has evolved with the advent of glucagon-like peptide-1 receptor agonists and sodium–glucose cotransporter-2 inhibitors, it is beneficial to continuously update evidence that may guide modern pharmacologic control." (PMID 40648963, 2025). "However, recently, the use of Glucagon-Like Peptide-1 receptor agonists (GLP-1RAs) has gained significant attention for their effectiveness in weight-loss and diabetes management and are increasingly being used as an alternative to invasive surgeries." (PMID 40458827, 2025). "Glucagon-like peptide-1 receptor agonists are effective treatments for obesity and diabetes." (PMID 41945470, 2025). "Glucagon-like peptide-1 receptor agonists (GLP-1 RAs) are a class of drugs originally developed to improve glycemic control in patients with diabetes; however, these agonists have subsequently demonstrated additional cardioprotective effects, including modest reductions in blood pressure (BP)." (PMID 41524068, 2025). "Initial drug repurposing efforts, or finding new uses for existing medications, have been primarily focused on trials of diabetes treatments such as pioglitazone, glucagon-like peptide 1 receptor (GLP1R) agonists, or sodium-glucose transporter 2 (SGLT2) inhibitors." (PMID 40034783, 2025). "In addition, GLP-1R has been suggested to play a neuroprotective role in diabetes-related neurodegeneration by increasing insulin sensitivity." (PMID 40274715, 2025). "The findings revealed that GLP-1R protein expression in diabetes rats was reduced, and 1,25-D3 reversed this change, which could activate GLP-1R to achieve the neuroprotective effect." (PMID 40224490, 2025). "In this multicenter, open-label, and single-armed prospective study, 48 patients with diabetes (including type 1 and type 2) at 3 hospitals in Japan treated with insulin or glucagon-like peptide 1 receptor agonists and performing SMBG used the app-cloud cooperation system for 24 weeks." (PMID 38241065, 2024). "The results of immunohistochemistry experiments showed that STZ-treated decreased the positive cells, mean density and H-score of GLP-1R, and daphnetin-treated increased these levels, which indicated that daphnetin-treated increased GLP-1R level of diabetes cognitive dysfunction rats." (PMID 39257395, 2024). "Preclinical studies suggest that GCGR/GLP-1R/glucose-dependent insulinotropic polypeptide (GIP) receptor triple agonists may also prove useful for the therapy of diabetes and obesity." (PMID 38879678, 2024).